IL10 (interleukin 10)
Diseases named in the same sentence as IL10 in open-access papers (continued):
Sharing a sentence is not in itself a finding about the gene and the disease.
endotoxemia (continued). "Exogenous administration of recombinant IL-10 protects mice from lethal endotoxemia by reducing TNF-α release." (PMID 19725984, 2009). "Furthermore, IL-6 demonstrates protective effects against LPS-induced endotoxemia by increasing the production of IL-10 and modulating cytokine responses, which includes the enhancement of hepatic antioxidant enzymes." (PMID 40564288, 2025). "Several inflammatory mediators, derived from the host cells, are responsible for most manifestations of endotoxemia, causing an increase in the production of endogenous cytokines, such as TNF-α and IL-6, IL-8, and IL-10, which play a critical role in inflammatory responses." (PMID 38338117, 2024). "The endotoxemia-induced increase in anti-inflammatory cytokine IL-10 was attenuated in subjects treated with atazanavir: 219 (95%CI: 152-318) pg/mL versus 377 (95%CI: 233-609) pg/mL in subjects in the placebo group (over time, both p<0.001, between groups p=0.01)." (PMID 37261364, 2023). "However, in another study of experimental mice endotoxemia, mTH was related to a significant increase of both plasma IL-10 and IL-6." (PMID 36012493, 2022). "Next, we wanted to examine whether myeloid-specific deletion of Cdk5 in mice exposed to LPS-induced endotoxemia would enhance systemic plasma Il-10 levels and contribute to increased survival." (PMID 34502552, 2021). "In this study, we investigated whether the deletion of Cdk5 in macrophages regulates Il-10 production through c-Maf during LPS-induced endotoxemia." (PMID 34502552, 2021). "In this study, we identified YB‐1 as an important regulator of the immune regulatory cytokine IL‐10 via its fourth intron region in endotoxemia and in I/R‐induced sterile inflammation and demonstrated that YB‐1 exerts both pro‐ and anti‐inflammatory properties in the course of inflammation." (PMID 28664613, 2017). "In accordance, VDR KO mice have shown to be more susceptible to LPS-induced endotoxemia, have higher expressions of inflammatory cytokines (e.g., TNF-α, IL-1a, IL-1β, IL-10, IL-21, and IFN-γ), and experience more weight loss, bleeding, ulceration, septic shock, and death compared to wild-type mice." (PMID 28066436, 2016). "The sustained higher levels of cytokines IL-6 and IL-10 at the later hours could be partially responsible for imparting a protective role in endotoxemia." (PMID 25759837, 2015). "Furthermore, the anti-inflammatory cytokines IL-10 and IL-1 receptor antagonist exhibited increased expression during endotoxemia, but were reduced by post-treatment with MAT.Ang-1." (PMID 23036162, 2012). "On the other hand, the lack of endogenous IL-10, a prototypic anti-inflammatory cytokine, resulted in increased levels of TNF and enhanced mortality in mouse models of endotoxemia, whereas in models of bacterial infection, endogenous IL-10 impairs the bacterial clearance." (PMID 19454012, 2009). "Likewise, BAM15 also attenuated other parameters of systemic inflammation, as indicated by serum cytokines (TNF-α, IL-6, and IL-10) and serum cell-free DNA (cf-DNA), which might be due to the reduction in endotoxemia and bacteremia." (PMID 35628259, 2022). "Moreover, we analyzed pro-inflammatory cytokines and chemokines in the plasma of Cdk5LysMCre and Cdk5flox mice during LPS-induced endotoxemia, since in vitro studies using c-Maf knockout macrophages showed elevated levels of Ccl5 and Il-1a in addition to Il-10." (PMID 34502552, 2021). "Therefore, our aim was to investigate whether Cdk5 deletion in myeloid cells modulates Il-10 production during endotoxemia." (PMID 34502552, 2021). "In addition, plasma Il-10 levels of Cdk5LysMCre were significantly elevated 4 h after LPS injection and showed a trend toward increased plasma Il-10 levels at 2 h and 24 h of LPS-induced endotoxemia compared with their Cdk5flox littermates." (PMID 34502552, 2021).
endotoxemia (continued). "The IL-10 is a potent anti-inflammatory factor in bacterial endotoxemia and crucial for maintaining homeostasis, which could be stimulated by LPS as a negative feedback by dampening a pro-inflammatory response and preventing inflammation caused by tissue injury." (PMID 32005962, 2020). "In addition, IL-10 and IFN-γ associated responses may cause a gain of pro-inflammatory activity, as shown in human models of endotoxemia." (PMID 26441914, 2015). "Thus, blocking TLR-4 or administering IL-6 or IL-10 might impart protection against endotoxemia in the clinical field." (PMID 25759837, 2015). "Interestingly, IL-10 knockout mice exhibit unregulated inflammatory activity exemplified by enhanced TNF-α accumulation, which is associated with a variety of pathogenic outcomes, including endotoxemia and intestinal inflammation." (PMID 19040745, 2008). "We here propose that the mechanism underlying this effect is not only due to the reported ability of probiotics in reducing endotoxemia but also to the specific antiinflammatory effect of S. clausii SF174 spores mediated by increased portal levels of IL‐10." (PMID 40207597, 2025). "We examined the influence of CRG, Ech, and CRG/ECh on the in vivo production of anti-inflammatory and proinflammatory cytokines (IL-10 and TNF-α, respectively) in an experimental endotoxemia model induced by LPS." (PMID 36233004, 2022). "We further detected a mild increase of Il-10 production in the plasma and lung tissue as well as in the BAL of Cdk5LysMCre mice during endotoxemia." (PMID 34502552, 2021). "Progressive endotoxemia can result in an acute respiratory distress syndrome (ARDS) and acute lung inflammation (ALI) and treatment with Il-10 is shown to improve survival in ALI mouse models." (PMID 34502552, 2021). "Additional studies using iron chelation in endotoxemia models also showed a decrease in LPS-induced activation of NF-κB and reduced plasma levels of TNF-α, IL-6, IL-1β and IL-10." (PMID 32466384, 2020). "In contrast, LPS-induced endotoxemia in mice was shown to be protected by MCP-1 administration, which increases plasma IL-10 levels, and to be exacerbated by anti-MCP-1 antibody administration, which increases the peak TNF-α and IL-12 levels." (PMID 28272428, 2017). "Pretreatment with IL-6 or IL-10 could provide a protection in endotoxemia by inhibiting tissue degradation as it has already been established in our prior studies that pretreatment with IL-6 lowers liver damage in experimental endotoxemia by modulating ROS production and cell infiltration." (PMID 25759837, 2015). "A possible/plausible regulator of this phenomenon is heme oxygenase-1 (HO-1), which is induced by LPS and provides defense against endotoxemia, including LPS-induced ARF, controlling the IL-6/IL-10 balance." (PMID 24376813, 2013). "Endotoxemia led to a rise in body temperature and inflammatory symptom scores and a rise in plasma TNF-α, IL-6, IL-10 and IL-1RA." (PMID 24358337, 2013). "The activation of macrophages by LPS is an important event during endotoxemia, LPS activates macrophages to produce cytokines such as TNF-α and IL-10." (PMID 23285207, 2012). "In adult horses with experimentally induced endotoxemia, IL-10 gene expression in whole blood was not higher at any timepoint in comparison with the baseline." (PMID 39273060, 2024). "When comparing ATB+DSS with P. aeruginosa (ATB+DSS+PA) and ATB+DSS mice, P. aeruginosa exacerbated loose stool in almost all mice, leaky gut parameters (bacteremia, FITC-dextran, and endotoxemia), systemic inflammation (TNF-α, IL-6, and IL-10), and liver damage (alanine transaminase)." (PMID 39546435, 2024). "In CLP alone, the Ezh2 inhibitor attenuated kidney damage (serum creatinine) and serum cytokines (TNF-α, IL-6, and IL-10) but not cell-free DNA, endotoxemia, and bacteremia." (PMID 37239864, 2023).
endotoxemia (continued). "In Candida-Bil Nep, probiotics improved survival rate, serum IL-6 (not TNF-α and IL-10), endotoxemia, and bacteremia with increased fecal butyric acid." (PMID 36969207, 2023). "While IL10+ B cells play no essential role in endotoxemia, IL10+ B cells decrease the numbers of CD8+ T cells during infection with murine cytomegalovirus and control the immune activation when the mice were challenged with anti-IgD antibodies." (PMID 37849749, 2023). "In an in vivo mouse model of LPS-induced endotoxemia, mice lacking Cdk5 in macrophages showed increased levels of c-Maf and elevated levels of Il-10 in lungs as well as in plasma, resulting in ameliorated survival." (PMID 34502552, 2021). "In addition, both probiotics also attenuated liver enzyme (alanine transaminase), oxidative injury (reduced MDA and increased GSH), serum cytokines (TNF-α, IL-6, and IL-10), and gut leakage (FITC-dextran assay and endotoxemia)." (PMID 35010955, 2021). "The cytokine profiles revealed that the adoptive transfer of M(IFNγ+LPS+IC) in mice with LPS-induced endotoxemia before LPS administration has a systemic impact on some pro-inflammatory cytokines but no detectable influence on IL-10." (PMID 31998290, 2019). "The relative number of anti-inflammatory Tregs and its capacity to produce IL-10 remained stable and did not change during endotoxemia." (PMID 29868038, 2018). "Likewise, in other organs glycine was reported reducing hepatic damage and improve the survival rate of endotoxemia mouse models by regulating TNF-a and IL-10 secretion." (PMID 30050902, 2018). "These in vitro results, indicating that IL-10 production can be enhanced by GBZ, confirmed that our strategy of targeting eIF2α phosphorylation to limit systemic inflammation and liver failure during endotoxemia was appropriate." (PMID 28659918, 2017). "In LPS-induced endotoxemia, activated ERK1/2 can induce higher expression of IL-10." (PMID 25387998, 2014). "We assumed that TNFα, IL-6 and IL-10 form an important fraction of gut derived nonbacterial factors, transported via mesenteric lymph and contributing to lung injury during endotoxemia." (PMID 24356325, 2013). "Horses from both experimental groups presented clinical signs and hematological changes in endotoxemia, including an increase in heart rate and body temperature, neutrophilic leukopenia, an increase in serum bilirubin, glucose, lactate, and an increase in TNF-α, IL-6, and IL-10." (PMID 38338117, 2024). "However, a subset of children (17%) with endotoxemia had ‘anergic’ type immature IL-10-secreting DCs which failed to drive T cell proliferation." (PMID 35185860, 2021). "Moreover, LA5 improved gut permeability defect (gut leakage) and leaky gut-induced systemic inflammation as indicated by FITC-dextran assay, ZO-1tight junction protein, endotoxemia, colon mucin production (gene expression of muc2) and serum cytokines (TNF-α, IL-6, and IL-10)." (PMID 33737543, 2021). "Therefore, we hypothesize that sesamol increases IL-10, decreases the production of TNF- and IL-1β to balance the SIR against LPS-induced hypotension and endotoxemia." (PMID 26839527, 2015). "This difference could be responsible for the protective effect of the lactic acid bacterium since IL-10 inhibits the synthesis of pro-inflammatory cytokines such as TNF-α and IL-1 in vitro and attenuate the increase in PAI-1 concentrations during human endotoxemia." (PMID 19835595, 2009).
hepatocellular carcinoma (99 papers, 2005 to 2025). A malignant tumor that arises from hepatocytes. "High IL10 expression has been associated with tumor progression and poor survival in hepatocellular carcinoma patients." (PMID 39006665, 2024). "Overall, the heterozygous model showed a marginal significant association only between IL-10 (-1082 A/G) and hepatocellular carcinoma risk (OR: 0.82, 95% CI: 0.67-1.00, 9 studies)." (PMID 37684564, 2023). "Taken together, the objective was to investigate the relationship between polymorphisms of IL-10 (-1082 A/G, -819 T/C, -592 A/C), and hepatocellular carcinoma by performing a meta-analysis." (PMID 37684564, 2023). "Findings suggest that IL-10 (-1082 A/G and − 819 T/C) polymorphisms are associated with hepatocellular carcinoma in ethnic-specific manner." (PMID 37684564, 2023). "For a subgroup of non-Asian population, there was a significant association between the IL-10 (-1082 A/G) and hepatocellular carcinoma in protection using the heterozygous model (OR: 0.60, 95% CI: 0.43–0.85, I2 = 30.3%, fixed effect model, four studies)." (PMID 37684564, 2023). "In the present meta-analysis, we assessed the role of three important SNPs in the IL-10 gene (-1082 A/G, -819 T/C and − 592 A/C) in the risk of hepatocellular carcinoma across eight countries." (PMID 37684564, 2023). "A published study reported that high levels of IL-10 reduced the risk of hepatocellular carcinoma by reducing hepatic inflammation, which in turn prevents the malignant transformation of liver cells." (PMID 37684564, 2023). "The SNP at the splice region of IL-10 (+1927) showed that the A/A genotype was related to a higher risk for hepatocellular carcinoma." (PMID 34207210, 2021). "However, in other cancers like cervical cancer and hepatocellular cancer, higher expression of IL-10 was a risk factor." (PMID 37501757, 2023). "Understanding of IL-10 genetic polymorphisms may help to estimate the influence of genetic alteration on the development of hepatocellular carcinoma." (PMID 37684564, 2023). "Overall, Il-10 (-819 T/C) was associated with hepatocellular carcinoma susceptibility under dominant model (OR: 1.25, 95% CI:1.05–1.48, I2 = 15.7%, fixed effect model, 8 studies), and heterozygous model (OR: 1.20, 95% CI: 1.00-1.43, I2 = 0.0%, fixed effect model, 8 studies." (PMID 37684564, 2023). "Several tumor-derived factors could be responsible for the decline of DC, e.g., increased serum levels of IL-10 correlate with profound numerical deficiency and immature phenotype of circulating DC subsets in patients with hepatocellular carcinoma." (PMID 33066260, 2020). "A recent report showed that YBX1 supports immune evasion in hepatocellular carcinoma cells by decreasing the release of important inflammatory cytokines such as IL10 and TGFβ, further underlining our findings of a negative regulation of apoptosis-related cytokines and chemokines in medulloblastoma." (PMID 32585856, 2020). "In the subsequent in vitro studies, IL-19 raised the level of TNF-α and IL-10 transcripts in hepatoma cells, which may cause liver inflammation and lead to hepatic damage." (PMID 23468852, 2013). "Lastly, due to the complexity of the etiology of hepatocellular carcinoma, there might be a contextual interaction between polymorphisms of IL-10 gene and other genes together with environmental/lifestyle related factors, which were beyond the scope of our study." (PMID 37684564, 2023). "This study aimed to assess the correlation between the genotyping of interleukin-10 (IL-10 polymorphism rs 1800871) and the incidence hepatocellular carcinoma (HCC) among patients with hepatitis C virus (HCV) treated with direct acting antivirals (DAAs)." (PMID 34710996, 2021). "Hepatoma cells also secrete immunosuppressive cytokines such as IL‐10 and TGF‐β, which further dampen the host's antitumor immune response." (PMID 40060195, 2025).
hepatocellular carcinoma (continued). "The prognostic impact of IL-10 has also been observed in other conditions, suchas unresectable hepatocellular carcinoma (HCC) and Coronavirus Disease 2019 (COVID-19)." (PMID 40026520, 2025). "It was also found in a mouse model that increased interleukin-10 (IL-10) production by MDSCs in hepatocellular carcinoma inhibited the secretion of interleukin-12 (IL-12) by DCs." (PMID 38609997, 2024). "A newly identified B cell subset contributes to tumor immune evasion in hepatocellular carcinoma by inhibiting T cell responses through PD-1 and IL-10." (PMID 39519376, 2024). "Our findings suggest IL-10 pertinent to AA and GG genotypes in -1082 A/G would be a protective role in hepatocellular carcinoma." (PMID 37684564, 2023). "MiR‐98 mimics notably elevate the levels of IL‐1β and TNF‐α in TAM under hepatocellular carcinoma conditions, but significantly lower IL‐10 and TGF‐β, meaning that M2 turns into M1, thus repressing EMT, invasion, and migration of SMMC7721 and HepG2 cells." (PMID 38098217, 2023). "Oscillibacter, as an anti-inflammatory bacterium, regulates T cell differentiation by reducing Th17 polarization, which secretes IL-17 cytokine, and promoting and maintaining the IL-10-producing Treg cells in the gut of a hepatocellular carcinoma mouse model." (PMID 37575984, 2023). "Our analysis highlights the need for additional studies on the role of the IL10 gene in the development of hepatocellular carcinoma, and the findings should be used to inform healthcare providers considering screening of genetic risk factors." (PMID 37684564, 2023). "There is a surge of individual studies that investigated the roles of IL-10 in patients with hepatocellular carcinoma." (PMID 37684564, 2023). "Our findings are consistent with a study that shows serum IL-10 levels were elevated in hepatocellular carcinoma patients compared with normal controls, but that they decreased after surgical resection." (PMID 36428795, 2022). "IL-10 has been previously shown to have an immunosuppressive role on circulating DCs in patients with hepatocellular carcinoma." (PMID 33540635, 2021). "M-MDSCs isolated from hepatocellular carcinoma patients secrete IL-10 and differentiate naïve CD4+ T-cells into Foxp3+CD25+ T-cells in in vitro cultures—an effect that was contact-dependent and blocked with anti-IL-10 antibodies." (PMID 34203451, 2021). "H22 hepatoma bearing mice treated with DCs and DCs stimulated by ESPs showed a decrease in IL-4, IL-6, or IL-10 compared with their levels in the PBS and ESP groups (p < 0.05)." (PMID 32692308, 2020). "At the same time, it was also found in this study that the levels of Treg-related immune cytokines (IL-2, IL-10, and TGFβ) were significantly increased in mice in the hepatoma-bearing model group." (PMID 33204731, 2020). "Hepatocellular carcinoma-derived exosomes can induce an immunosuppressive macrophage phenotype by upregulating PD-L1 ligand expression and overexpressing IL-10." (PMID 32488850, 2020). "In patients with chronic hepatitis B infection and hepatocellular carcinoma it was found that the CD4+ CTL also produced IL-10 which inhibited the function of CD8+ CTL." (PMID 30323982, 2018). "Together, DCs generated in hepatoma environments is mainly crucial for B-cell activation-elicited IL-10 production." (PMID 27853178, 2016). "For example, the ERK1/2 and p38MAPK pathways were shown to be involved in the induction of HO-1 by arsenite in hepatoma cells and only the p38MAPK was shown to mediate the induction of HO-1 by IL-10 in murine macrophages." (PMID 24927128, 2014). "IL-10 in serum from patients with hepatocellular carcinoma correlates with decreased number of DCs and immature DCs subsets." (PMID 20214814, 2010). "Studies performed on murine hepatocellular carcinoma showed that impaired migration of lymphocytes to neoplastic liver tissue coincided with elevated production of IL-10 by endothelial cells of tumour neovessels." (PMID 17325703, 2007).